TGFBR3 (transforming growth factor beta receptor 3)
Diseases named in the same sentence as TGFBR3 in open-access papers (continued):
Sharing a sentence is not in itself a finding about the gene and the disease.
Hepatic fibrosis (3 papers, 2017 to 2025). The presence of excessive fibrous connective tissue in the liver. "A recent study showed that Schistosoma-sourced sja-miR-2162 deliveried and overexpressed by rAAV8 could inhibit the expression of TGFBR3 with high efficiency, which ultimately promoted hepatic fibrosis." (PMID 34521449, 2021). "Additionally, the target gene of miR-590-5p (CCR5) can facilitate the progression of liver fibrosis in mice, and the TGFβ receptor TGFBR3 plays a pivotal role in the development and progression of liver cirrhosis." (PMID 28355233, 2017).
migraine (3 papers, 2022 to 2025). "This probably suggests that the TGFBR3 gene is a risk factor for migraine but protects cognitive function in migraineurs." (PMID 35783123, 2022). "Further research is needed to determine the pathological mechanism of the SCD-related variant in TGFBR3 in individuals with migraine." (PMID 35783123, 2022). "In conclusion, this study revealed that the SNP rs144191744 (in TGFBR3) was significantly correlated with the likelihood of SCD in a cohort of patients with migraine, especially in the EM, MoA, and female subgroups." (PMID 35783123, 2022). "Another recent GWAS including 2084 Taiwanese patients and 11,822 age- and sex-matched controls identified two loci, rs10493859 in TGFBR3 and rs13312779 in FGF23, both functionally relevant to vascular function and migraine, to be significantly associated with self-reported headache." (PMID 36800925, 2023). "Previously, we found that the TGFBR3 gene protects patients from SCD under migraine conditions." (PMID 35783123, 2022).
oral cancer (3 papers, 2020 to 2021). "In support of this notion, TGFBR3 is downregulated in oral cancer-associated fibroblasts relative to that in normal fibroblasts (NFs) and negatively regulated by TGF-β in CAFs and cancer cells." (PMID 32471132, 2020). "Thus, the detailed mechanism by which GIPC1 mediates TGFBR3-associated inhibition of oral cancer cell migration and invasion warrants further investigation." (PMID 32471132, 2020). "In the present study, we found a reduced expression of TGFBR3 in oral cancer patients in both the TCGA-HNC dataset and clinical specimens in NCKU hospital." (PMID 32471132, 2020). "Ectopic expression of TGFBR3 decreased migration and invasion of oral cancer cells and lymph node metastasis of tumors, whereas depletion of TGFBR3 had the opposite effect." (PMID 32471132, 2020). "Ectopic overexpression of TGFBR3 decreased migration and invasion of oral cancer cells, while the silencing of TGFBR3 had the opposite effects." (PMID 32471132, 2020). "The present study aims to dissect the role of TGFBR3 in oral cancer cells and examine the molecular mechanism whereby TGFBR3 mediates the crosstalk between HNC and stromal cells." (PMID 32471132, 2020). "In an effort to elucidate the mechanism underlying the down-regulation of TGFBR3 in oral cancer cells, we identified an inverse relationship between the expression of TGFB1 and TGFBR3 using the TCGA-HNC database." (PMID 32471132, 2020). "Collectively, these data indicated that TGFBR3 mRNA and protein abundance were significantly lower in oral cancer and suggested a role of TGFBR3 in the oncogenesis of oral cancer." (PMID 32471132, 2020). "We demonstrated that TGFBR3 induces the abundance of secreted angiogenin (ANG), a known pro-angiogenic factor, and ANG is essential and sufficient to mediate TGFBR3-dependent inhibition of migration and invasion of oral cancer cells." (PMID 32471132, 2020). "This study should facilitate the possibility of using TGFBR3-mediated tumor suppression for oral cancer treatment." (PMID 32471132, 2020). "We further examined the paracrine effect of CM derived from TGFBR3-manipulated oral cancer cells on cancer cells, CAFs, and ECs." (PMID 32471132, 2020). "To elucidate the role of TGFBR3 in TGF-β signaling in oral cancer cells, we determined the effect of TGFBR3 expression on phosphorylation of SMAD2/3, an activation mark of the canonical TGF- β pathway, with or without SB431542, an inhibitor of TGFBR1." (PMID 32471132, 2020). "To dissect the role of TGFBR3 in oral cancer cells, we first examined the abundance of TGFBR3 in a panel of oral cancer lines." (PMID 32471132, 2020). "We further identified ANG, a previously known tumor promotor that mediates TGFBR3-dependent suppression of migration and invasion of oral cancer cells." (PMID 32471132, 2020). "In SMAD4-positive OC-2 oral cancer cells, TGFBR3-mediated suppression requires both of its cytoplasmic interacting partners ARRB2 and GIPC1." (PMID 32471132, 2020). "We observed that CM collected from TGFBR3-overexpressing OC-2 cells decreased migration and invasion of OC-2 cells and CAFs isolated from oral cancer specimens, and inhibited tube formation of human umbilical vein ECs (HUVECs), without affecting proliferation of CAFs or ECs." (PMID 32471132, 2020). "We next investigated whether ARRB2 or GIPC1 plays a role in SMAD4-independent, TGFBR3-mediated migration and invasion of oral cancer cells by knocking down ARRB2 or GIPC1 in TGFBR3-overexpressing CAL-27 cells." (PMID 32471132, 2020). "Indeed, TGF-β1 treatments of OC-2 oral cancer cells significantly decreased TGFBR3 mRNA and protein abundance and promoted cell migration and invasion." (PMID 32471132, 2020). "Notably, in SMAD4-deficient CAL-27 oral cancer cells, only GIPC1 is essential for TGFBR3-induced suppressive activity." (PMID 32471132, 2020). "TGFBR3 has been shown to be a tumor suppressor in several cancer types, including oral cancer." (PMID 32471132, 2020).
oral cancer (continued). "However, the role and action mechanism of TGFBR3 in mediating the crosstalk between oral cancer cells and stromal cells remains elusive." (PMID 32471132, 2020). "To investigate whether TGFBR3 expression was dysregulated in oral cancer specimens, we first performed an in silico analysis by using publicly available gene expression datasets for HNC from Oncomine and The Cancer Genome Atlas (TCGA)." (PMID 32471132, 2020). "In SMAD4-positive OC-2 oral cancer cells, both ARRB2 and GIPC1 participate in TGFBR3-mediated inhibition of migration and invasion." (PMID 32471132, 2020). "In this study, we observed a down-regulation of TGFBR3 in oral cancer, a subtype of head and neck cancer (HNC), and patients with low TGFBR3 had poor clinical outcomes." (PMID 32471132, 2020). "Because TGF-β1 enhanced migration and invasion of HNC cells, we next investigated the role of TGFBR3 in TGF-β1-induced migration and invasion of oral cancer cells." (PMID 32471132, 2020). "Furthermore, overexpression of TGFBR3 reduced the activation of TGF-β1-mediated SMAD signaling and aggressive cell behaviors in OC-2 oral cancer cells." (PMID 32471132, 2020). "Previously, we found a set of retinoid signaling related genes, including ADHFE1, ALDH1A2, CRBP1, PAX9, GDF10, TGFBR3, and PPARγ were frequently hypermethylated and downregulated in OSCC patient samples, suggesting the severe molecular defects in RA metabolism in oral cancer." (PMID 32238162, 2020).
papillary carcinoma (3 papers, 2021 to 2024). A malignant epithelial neoplasm characterized by a papillary growth pattern. "We were also able to expand TGFBR3’s role in renal cancer to papillary carcinomas as well." (PMID 33819300, 2021).
thyroid cancer (3 papers, 2019 to 2024). "Furthermore, compared with well-differentiated tumors, poorly differentiated tumors have a low expression of TGFBR3, suggesting that PTC may progress to poorly differentiated thyroid cancer in the late stage." (PMID 31126066, 2019).
adenoma (2 papers, 2017 to 2024). A neoplasm arising from the epithelium. "Noteworthy, the numbers of RNA interactors of some MP-RNAs (WDR62, TGFBR3, RN7SL5P, RMRP, MIR663AHG, AJ009632.2, CDKL1, OPRD1, PLOD1, AL117692.1, ATP13A2, EPB41) in cancer tissue were significantly increased compared with that in paracancer and adenoma." (PMID 38773399, 2024).
Behçet's disease (2 papers, 2020). "Furthermore, the TGFBR3 rs1805110 polymorphism was also found to be associated with Behcet's disease in both Caucasians and the Chinese Han population." (PMID 33062074, 2020). "Another polymorphism, TGFBR3 rs1805110, despite not being previously investigated in the context of SCD, was associated with Behcet's disease, an inflammatory disorder in the Chinese population characterized by blood vessel inflammation." (PMID 33062074, 2020).
cervical cancer (2 papers, 2020 to 2024). A primary or metastatic malignant neoplasm involving the cervix. "In light of these current studies, we proposed that TGFBR3 or HMGCS1 suppressed cervical cancer progression through negatively regulating the Wnt/β‐catenin pathway or positively promoting phosphorylation of p27 and CHK2, at least partially." (PMID 32491253, 2020). "In conclusion, our results demonstrate that the STAT3‐miR‐223‐HMGCS1/TGFBR3 axis functions as a key signaling pathway in cervical cancer progression and provides a new therapeutic target." (PMID 32491253, 2020). "However, more in‐depth investigations of the role of TGFBR3 or HMGCS1 in cervical cancer progression are required in future." (PMID 32491253, 2020). "TGFBR3 and HMGCS1 acted as repressors of cervical cancer development, attenuating the activity of colony formation in vitro." (PMID 32491253, 2020). "Taken together, these results suggest that TGFBR3 and HMGCS1 are negative regulators of cervical cancer development." (PMID 32491253, 2020). "As the downstream targets of miR‐223, we hypothesized that TGFBR3 and HMGCS1 might function as repressors in cervical cancer development." (PMID 32491253, 2020).
cholelithiasis (2 papers, 2020 to 2021). The presence of crystallized deposits forming in the gallbladder or biliary tree, primarily composed of cholesterol, bilirubin, and bile. "Collectively, the present findings suggest that individuals with the GG and CGG haplotypes of TGFBR3 present significant lipid profile alterations and could be associated with the occurrence of pneumonia, while the non-GG haplotypes was associated with the occurrence of cholelithiasis." (PMID 33149723, 2020).
colorectal cancer (2 papers, 2014 to 2020). A primary or metastatic malignant neoplasm that affects the colon or rectum. "Analysis of expressed mutated surface genes revealed recurrent mutations in genes belonging to pathways known to be involved in colorectal cancer, including the WNT (LRP5 and FZD10), TGFβ (TGFBR3 and ACVR1B) and RTK-Ras (EGFR and ERBB3) signaling pathways." (PMID 25193853, 2014).
laryngeal squamous cell carcinoma (2 papers, 2020 to 2022). A squamous cell carcinoma that arises from the larynx. "Results in LSCC showed that circ_0042666 regulates miR-223/TGFBR3 expression in laryngeal squamous cell carcinoma cells." (PMID 36046345, 2022). "Wei Z found that hsa_circ_0042666 regulated laryngeal squamous cell carcinoma (LSCC) cell proliferation and invasion by the miR-223/TGFBR3 axis." (PMID 32931492, 2020).
liver disease (2 papers, 2021 to 2024). "SULF2 influences fibrotic liver disease by interacting with the TGF-β1/Smad pathway, and it appears that Transforming Growth Factor Beta Receptor 3 (TGFBR3) plays a significant role in mediating the activation of the TGF-β1 signaling pathway by SULF2." (PMID 38540990, 2024). "We demonstrate here that SULF2 exerts its effect on fibrotic liver disease via its interplay with the TGF-β1/Smad pathway and that the TGFBR3 likely plays an important role in the SULF2 mediated activation of the TGF-β1 signaling pathway." (PMID 34771445, 2021).
osteoarthritis (2 papers, 2022 to 2025). A noninflammatory degenerative joint disease occurring chiefly in older persons, characterized by degeneration of the articular cartilage, hypertrophy of bone at the margins and changes in the synovial membrane. "In IL-1β-stimulated osteoarthritis, the inhibitory effect of SNHG5 on the apoptosis of chondrocytes and inflammation is offset by silencing TGFBR3." (PMID 36180862, 2022).
osteoporosis (2 papers, 2021 to 2026). A condition of reduced bone mass, with decreased cortical thickness and a decrease in the number and size of the trabeculae of cancellous bone (but normal chemical composition), resulting in increased fracture incidence. "These three SNPs belong to the genes DGKB, BTNL2, and TGFBR3 that were indicated in previous genome wide association studies with CVD (DGKB), rheumatoid arthritis and sarcoidosis (BTNL2), and bone mass and osteoporosis (TGFBR3), respectively." (PMID 34201265, 2021).
osteosarcoma (2 papers, 2022 to 2024). A usually aggressive malignant bone-forming mesenchymal neoplasm, predominantly affecting adolescents and young adults. "A study has shown that TGFBR3, regulated by miR-323b-3p, plays a role in tumor inhibition in the occurrence and development of osteosarcoma." (PMID 39404708, 2024). "MiR-323b-3p is upregulated and TGFBR3 is downregulated in osteosarcoma to evoke tumorigenesis, with the opposite expression pattern being true in pulmonary metastasis where TGFBR3 acts as a tumor promoter for the development of pulmonary metastasis." (PMID 36358747, 2022).
ovarian tumor (2 papers, 2016 to 2017). "Further histochemical and molecular analyses provided evidence of overactivation of TGFBR1 in the granulosa cell compartment during ovarian pathogenesis in TGFBR1-CAG9Cre mice, along with upregulation of Gli1 and Gli2 and downregulation of Tgfbr3 in ovarian tumor tissues." (PMID 29221447, 2017). "Hence, reduced expression of TGFBR3 may facilitate the pathogenesis of ovarian tumors via attenuating inhibin function and potentiating activin signaling." (PMID 27344183, 2016).
Priapism (2 papers, 2020 to 2024). A painful and harmful medical condition in which the erect penis doesn't return to its flaccid state, despite the absence of both physical and psychological stimulation, within four hours. "A previous report suggested the association of TGFBR3 rs7526590 with priapism in individuals with SCD." (PMID 33062074, 2020). "Polymorphisms in TGFBR3 have been previously associated with clinical manifestations in SCD, such as pain crisis, ACS, infection, stroke, leg ulcers, priapism, osteonecrosis, and PH." (PMID 33062074, 2020).
adenoid cystic carcinoma (1 paper, 2017). A malignant tumor arising from the epithelial cells. "In 23 non-MECA salivary cancers, however, we did identify high TGFBR3 staining in a subset of adenoid cystic carcinoma (ACC), epithelial myoepithelial carcinoma, and polymorphic low-grade adenocarcinoma samples." (PMID 29084941, 2017).
aortic root dilatation (1 paper, 2018). "Interestingly, both father and brother, exhibiting aortic root dilatation, and sister of proband, in whom upper range of normal aortic root dimensions were observed, showed TGFBR3 mutation, thus suggesting a cosegregation of TGFBR3 variant with the presence of aortic root dilatation." (PMID 30255099, 2018).
atherosclerosis (1 paper, 2023). A disease characterized by the build-up of fatty material and calcium deposition in the arterial wall resulting in partial or complete occlusion of the arterial lumen. "Here, we verified the presence of protective circRNAs in exosomes which can delay the development of atherosclerosis through the analysis of the ceRNA network axis of circ_0001785/miR-513a-5p/TGFBR3." (PMID 37794449, 2023). "In summary, we demonstrate that circ_0001785 protects against endothelial cell injury by sponging miR-513a-5p to upregulate TGFBR3, thereby slowing the onset of atherosclerosis, which improves our understanding of the endogenous mechanisms of atherosclerotic plaque formation." (PMID 37794449, 2023). "Our results demonstrated a new biomarker, exosome-derived circ_0001785, for atherogenesis, which can reduce endothelial cell injury and thus delay atherogenesis through the miR-513a-5p/TGFBR3 ceRNA network mechanism, providing an exosome-based intervention strategy for atherosclerosis." (PMID 37794449, 2023).
autoimmune disease (1 paper, 2025). A disorder resulting from loss of function or tissue destruction of an organ or multiple organs, arising from humoral or cellular immune responses of the individual to their own tissue constituents. "Interestingly, the TGFBR3, THSD7A, and NTNG1 MNTAgs also exhibit podocyte preference expression, supporting the important pathological contributions of podocyte injury to the kidney-limited autoimmune disease of MN." (PMID 40149392, 2025).
bacteremia (1 paper, 2020). "A previous study performed in individuals with SCA, the majority of whom presented Streptococcus pneumoniae infection, identified that a polymorphism in TGFBR3 was associated with increased susceptibility to bacteremia." (PMID 33149723, 2020).
breast tumours (1 paper, 2023). "ACVR1C, TGFBR2, TGFBR3, ACVR2A, ACVR1, BMPR1A and BMPR2 were lower in breast tumours while ACVR1B and BMPR1B exhibited relatively higher expression levels in paired tumours compared with normal breast tissues, in the TCGA_BRCA cohort." (PMID 37333824, 2023).
cervical squamous cell carcinoma (1 paper, 2020). A squamous cell carcinoma arising from the cervical epithelium. "miR‐223 targeted the 3′‐UTRs of TGFBR3 and HMGCS1 and suppressed their expression, leading to increased anchorage‐independent growth and cervical squamous cell carcinoma (CSCC) tumor growth in vitro and in vivo." (PMID 32491253, 2020).
cervical tumor (1 paper, 2020). "miR‐223 was highly expressed in cervical tumor tissues, whereas TGFBR3 or HMGCS1 was significantly downregulated." (PMID 32491253, 2020).
cryptorchidism (1 paper, 2017). The failure of one or both testes of a male fetus to descend from the abdomen into the scrotum during the late part of pregnancy. "In contrast, studies in knockout mice and genome-wide association studies have shown that INSL3 and TGFBR3 are involved in the onset of cryptorchidism." (PMID 29197384, 2017).
endometrial adenocarcinoma (1 paper, 2022). "After MDGA1 was removed, the remaining candidate hub genes (RECK, CFL2, TGFBR3, TPM2, and C10ORF91) affecting the survival rate of endometrial adenocarcinoma in the MEbrown module and MEturquoise module were selected." (PMID 35123404, 2022).
endothelial dysfunction (1 paper, 2020). In vascular diseases, endothelial dysfunction is a systemic pathological state of the endothelium (the inner lining of blood vessels) and can be broadly defined as an imbalance between vasodilating and vasoconstricting substances produced by (or acting on) the endothelium. "Carriers of the minor allele (A/G+A/A) of the TGFBR3 rs1805110 polymorphism also had higher endothelin levels, which suggests a greater propensity of presenting vasoconstriction events and endothelial dysfunction." (PMID 33062074, 2020).
esophageal squamous cell carcinoma (1 paper, 2024). Esophageal squamous cell carcinoma (ESCC) is a type of esophageal carcinoma (EC) that can affect any part of the esophagus, but is usually located in the upper or middle third. "Down-regulation of TGFBR3 enhanced the malignant phenotype of esophageal squamous cell carcinoma." (PMID 39404708, 2024).
floor of mouth cancer (1 paper, 2020). "3-mRNA (TGFBR3、KLHL40 and HOXC13) model was identified in the network and that was associated with the clinical outcome of floor of mouth cancer according to univariate and multivariate Cox proportional regression analyses." (PMID 32931492, 2020).
hemangioendothelioma (1 paper, 2019). A vascular proliferation characterized by the presence of prominent endothelial cells and the formation of vascular channels. "Overexpression of let‐7a mimics resulted in smaller hemangioendothelioma, which is similar to knockdown of Tgfbr3." (PMID 30467960, 2019). "Particularly, we observed that let‐7a/TGFBR3 was required for hemangioendothelioma growth in the animal study, which could be an approach for in vivo strong evidence." (PMID 30467960, 2019).